MIR140 (microRNA 140)
Synonyms: hsa-mir-140; MIR-140; MIRN140; SEDN; miRNA140
Gene: MicroRNA gene on chromosome 16 (69,933,081 to 69,933,180, forward strand). Ensembl gene ENSG00000208017.
Gene Ontology:
Biological process: miRNA-mediated post-transcriptional gene silencing
Cellular component: RISC complex
Gene-disease validity (ClinGen):
ClinGen rates the evidence that MIR140 causes each of these diseases.
spondyloepiphyseal dysplasia, nishimura type (autosomal dominant): Limited. Spondyloepiphyseal dysplasia Nishimura type is characterized by spondyloepiphyseal dysplasia, craniosynostosis, cataracts, cleft palate and intellectual deficit.
Homologues: Orthologues: chimpanzee ptr-mir-140 (100% identical), pig MIR140 (99% identical), rat Mir140 (94% identical), macaque mml-mir-140 (93% identical), tropical clawed frog xtr-mir-140 (83% identical), zebrafish mir140 (82% identical), dog MIR140 (81% identical), rabbit MIR140 (79% identical), guinea pig MIR140 (70% identical), mouse Mir140 (70% identical).
Diseases named in the same sentence as MIR140 in open-access papers:
MIR140 is named in the same sentence as 9 diseases in open-access papers, as found by Europe PMC text mining. Sharing a sentence is not in itself a finding about the gene and the disease. The quoted sentences say what the papers report.
spondyloepiphyseal dysplasia (3 papers, 2019 to 2023). An osteochondrodysplasia that results in abnormalities of bone growth in the vertebral column and the epiphysis. "A gain-of-function mutation of the chondrocyte-specific microRNA, miR-140-5p, encoded by the MIR140 gene, causes spondyloepiphyseal dysplasia, Nishimura type (SEDN, also known as SED, MIR140 type; MIM, 611894)." (PMID 36711926, 2023).
hearing loss (1 paper, 2024). "Examples of such genetic diseases include hearing loss associated with MIR96 mutations, eye disorders linked to MIR184 mutations, and skeletal dysplasia involving MIR140 mutations." (PMID 39457367, 2024).
Intellectual disability (1 paper, 2021). "In GMCK-RD, a number of novel genes have been identified, resulting in improved biological understanding of disease mechanisms and better patient care as exemplified by KAT6A (intellectual disability), SLC12A5 (epilepsy of infancy), and MIR140 (skeletal dysplasia)." (PMID 33726816, 2021).
osteoarthritis (1 paper, 2020). A noninflammatory degenerative joint disease occurring chiefly in older persons, characterized by degeneration of the articular cartilage, hypertrophy of bone at the margins and changes in the synovial membrane. "Deletion of Mir140 in mice leads to a skeletal phenotype including an osteoarthritis (OA)-like disease." (PMID 32660984, 2020). "Deletion of the entire Mir140 locus in mice results in growth retardation and early-onset osteoarthritis-like pathology; however, the relative contribution of miR-140-5p or miR-140-3p to the phenotype remains to be determined." (PMID 32660984, 2020).
MIR140 also shares sentences with these, for which no sentence is quoted: skeletal dysplasia (2 papers); gastric cancer (1); genetic diseases (1); infection (1); tumor (1).